POLE (DNA polymerase epsilon, catalytic subunit)
Diseases named in the same sentence as POLE in open-access papers (continued):
Sharing a sentence is not in itself a finding about the gene and the disease.
endometrial cancer (continued). "However, endometrial cancer patients with POLE mutations get better clinical results after appropriate treatment, which can guide clinical practice." (PMID 40761799, 2025). "Notably, the amino acid mutation p.Ala456Pro (p.A456P; c.1366G>C) identified on exon 14, is situated in the exonuclease domain and has been suggested as a recurrent somatic aberration and identified as a pathogenic POLE hotspot mutation for endometrial cancer." (PMID 40873566, 2025). "Somatic mutations in POLE are frequently observed in endometrial cancer." (PMID 41278281, 2025). "Beyond immunotherapy, POLE mutations also indicate that traditional chemotherapy may be less critical for achieving optimal outcomes in this subset of endometrial cancers." (PMID 40072110, 2025). "POLE-mutated endometrial cancers have repeatedly shown to harbor an excellent prognosis." (PMID 40958870, 2025). "While POLE A456P has been suggested to be pathogenic for endometrial cancer, its pathogenicity remains of unknown significance for CRC." (PMID 40873566, 2025). "These triple-classifiers might be classified as POLEmut endometrial cancers if they carry a pathogenic POLE exonuclease domain mutation (EDM) as identified through whole-exome sequencing (WES) data." (PMID 39980551, 2025). "However, the potential of immunotherapy for endometrial cancer (EC) with POLE mutations remains underexplored." (PMID 39931062, 2025). "In addition, a recent real-world cohort study from the United Kingdom assessed the clinical and genomic characteristics of POLE-mutant endometrial cancers and found that these cases were associated with a favorable prognosis." (PMID 39931062, 2025). "The treatment of POLE mutated endometrial carcinoma often involves surgical resection followed by a tailored approach to adjuvant therapy, with a strong consideration for minimizing additional treatments due to the excellent prognosis associated with this molecular subtype." (PMID 40004914, 2025). "The mutations in DNA polymerase ε (POLE) are recognized as key features of EC and may confer survival benefits in endometrial cancer patients undergoing anti-PD-1/PD-L1 therapy." (PMID 38238314, 2024). "Moreover, we also observed a trend to earlier age of onset for colorectal cancers and endometrial cancers with POLE ExoD driver occurring in conjunction with other POLE variants." (PMID 38282550, 2024). "Furthermore, the POLE P286R mutation inhibits tumor growth and facilitates the infiltration of cytotoxic T cells in human endometrial cancers." (PMID 38238314, 2024). "In this analysis, historical patient tissue samples of 880 women with high-intermediate risk endometrial cancer were re-evaluated and categorized into the relevant TCGA subgroups: POLE ultra-mutated, microsatellite instability (MSI) hypermutated, copy-number low, and copy-number high." (PMID 38539507, 2024).
endometrial cancer (continued). "Notably, we observed a positive correlation between POLE mutations and the infiltration abundance of various immune cells, including T cell, B cell, and Dendritic cells in endometrial cancer." (PMID 38238314, 2024). "The activation of the cGAS-STING pathway by POLE mutation likely contributes to the advantageous survival of endometrial cancer patients with POLE mutations, as the cGAS-STING pathway has been associated with anti-tumor activity through the stimulation of inflammatory genes." (PMID 38238314, 2024). "POLE mutated endometrial carcinomas may represent a subspecific type of tumors harboring a more favorable prognosis." (PMID 38262245, 2024). "We report an endometrial cancer patient harbored a novel somatic POLE T278K mutation." (PMID 36765365, 2023). "In the TCGA classification, the POLE mutated/ultramutated group of endometrial cancers was reported as a subtype of neoplasm that showed an excellent prognosis independently of other clinicopathological variables, such as high-grade tumours and an advanced development stage." (PMID 37958329, 2023). "In summary, we report an endometrial cancer patient harbored a novel somatic POLE T278K mutation." (PMID 36765365, 2023). "In another early case report, a 57-year-old woman with recurrent, multi-therapy-resistant, stage III endometrial cancer with a POLE P286R mutation showed sustained response to α-PD-1, including regression of abdominal, retroperitoneal and pelvic deposits 7 months after follow-up." (PMID 37388540, 2023). "It is well known that there is already a well-established UCEC molecular classification by previous studies using TCGA, which classified endometrial cancer into four subtypes: POLE ultra-mutated, microsatellite instability hyper-mutated, copy-number low, and copy-number high." (PMID 36726804, 2023). "For example, molecular approaches to tumor profiling have revolutionized the characterization of endometrial cancers, which can now be classified according to DNA polymerase epsilon (POLE) mutation status, MSI status, and the number of somatic copy number alterations." (PMID 37628794, 2023). "POLE variants may elicit an intratumoral T cell response in endometrial cancer, colorectal cancer, meningiomas, and high-grade gliomas with an increased number of CD8+ tumor-infiltrating lymphocytes." (PMID 37990341, 2023). "For example, POLE hypermutation and deficient mismatch repair (dMMR) endometrial cancers may be more sensitive to PD-1/PD-L1 inhibitor-based immunotherapy because they are associated with high mutational burden and significant immune infiltration." (PMID 37886684, 2023). "At the moment, it is unknown if POLE mutation is directly linked to the propensity to avert deregulation of TGFβ signaling in this subtype of endometrial carcinoma." (PMID 37958433, 2023). "In addition, the ratio of pathogenic/likely pathogenic alterations in POLE in the exonuclease domain was only 1.4% (7.3% in the TCGA), supporting the favorable prognosis of POLE-mutated endometrial carcinomas." (PMID 38201563, 2023). "C2 was composed of UCEC, a subtype of endometrial carcinoma known to have POLE mutations." (PMID 37856446, 2023).
endometrial cancer (continued). "Our results suggest that P286R, V411L, R375Q, and P452L are pathogenic POLE hotspot EDMs in endometrial cancer and affect the malignant behavior of tumor cells, which may provide new insights into the pathogenesis of endometrial cancer." (PMID 36313640, 2022). "POLE-mutated colorectal and endometrial cancers are associated with better prognosis and may exhibit favorable responses to immunotherapy." (PMID 35812186, 2022). "Although in lower percentages than in endometrial cancer, in ovarian cancer there are also cases exhibiting a POLE mutation and dMMR status, thereby the presence of these alterations could determine a niche to offer ICIs in ovarian cancer." (PMID 36010253, 2022). "There is a precedent of a protective effect of mutations in POLE in endometrial cancer." (PMID 36514795, 2022). "Thus, the associations of newly identified EDMs with the clinical outcomes and tumor cell behavior should also be considered when interpreting the POLE mutations in endometrial cancer." (PMID 36313640, 2022). "In endometrial cancer, a n-terminal exonuclease mutation in POLE leads to a hypermutant phenotype." (PMID 36514795, 2022). "Genome sequencing applied to cancer patients demonstrates that 3% of colorectal cancers and 7% of endometrial cancers contain mutations involving the exonuclease domain of POLE and are associated with high levels of single-nucleotide polymorphisms (SNPs) in this gene." (PMID 36672794, 2022). "In 2013, The Cancer Genome Atlas (TCGA) Research Network identified at least four groups of endometrial cancer patients, characterized by different prognoses (POLE-mutated or ultra-mutated; microsatellite instability or hypermutated; copy number low; copy number high)." (PMID 36553988, 2022). "Regarding the role of POLE mutations in endometrial cancer, most studies are focused on the association of POLE mutations with clinical outcomes and antitumor immune responses, and only a few studies investigated the role of POLE mutations in chemoresistance." (PMID 36313640, 2022). "To explore whether the good prognosis in the EDM group is associated with chemosensitivity, we overexpressed wildtype POLE or POLE variants in endometrial cancer cells and examined the response to different doses of cisplatin." (PMID 36313640, 2022). "Hence, other mechanisms, in addition to MSI, confer high TMB, e.g., the polymerase epsilon (POLE) mutation in endometrial cancer." (PMID 35158899, 2022). "In the 2020 ESGO-ESTRO-ESP guidelines, all POLE-mutated endometrial carcinomas up to FIGO stage II are included in the low-risk prognostic group, regardless of other clinicopathological features, such as tumor grade, histotype, LVSI, and depth of myometrial invasion." (PMID 35892892, 2022).
endometrial cancer (continued). "All these findings are consistent with the literature as CD4, CD8, FoxP3, and PD1 are inflammation markers, and POLE-mutated endometrial carcinomas, usually with a better prognosis than POLE WT, with higher abundance of A1 areas, are described to have large lymphocyte populations." (PMID 35217454, 2022). "Both MSI-positive endometrial cancers and POLE-mutated endometrial cancers have high neoantigen loads and immunogenic phenotypes, which may explain the high immune cell fraction in EC5." (PMID 33429363, 2021). "Therefore, endometrial cancer from younger patients is associated with POLE mutations, mismatch repair defects, high mutation load and better survival outcomes." (PMID 33879792, 2021). "Recent molecular studies, most notably the work from The Cancer Genome Atlas (TCGA) project, have shown that four endometrial cancer molecular classes can be distinguished; POLE ultra-mutated, microsatellite instable hypermutated, copy-number-low, and copy-number-high." (PMID 33082238, 2021). "POLE is mutated in many cancers, including pancreatic, ovarian, colorectal, and endometrial cancer." (PMID 34065218, 2021). "Moreover, POLE mutations were identified as a significant signature predicting OS and response to immunotherapy of Chinese patients with endometrial carcinomas." (PMID 34950188, 2021). "In addition, POLE-mutant microsatellite stable (MSS) tumors have been associated with high tumor mutation burden (TMB) in endometrial cancer." (PMID 33378353, 2020). "Evidence in support of this theory is the observation that tumor infiltrating and peritumoral lymphocytes are increased and that cytotoxic activities in CD8+ and CD4+ lymphocyte populations are heightened in POLE mutated endometrial cancers, similar to hypermutated MSI tumors." (PMID 32838755, 2020). "In this study, the co-occurrence of p190A and POLE mutations was observed in endometrial cancer." (PMID 32457342, 2020). "Germline variants within the exonuclease domains of the DNA replication and proof-reading polymerases POLD1 and POLE have been identified as dominantly inherited predispositions in colorectal cancer and have also been implicated in susceptibility to endometrial cancer." (PMID 32854222, 2020). "For example, the mutation subtypes of endometrial cancer have the highest adjusted RI (0.56) as compared to the integrated solution, which is consistent with the fact that POLE and MSI are the two major prognostic subtypes that are predominantly defined through mutation burden." (PMID 33272320, 2020). "In this study, we integrated whole exome sequencing data, patient clinical information, and the RNA sequencing data of the Uterine Corpus Endometrial Carcinoma (UCEC) project in the TCGA database for combinational analysis to elucidate the possible mechanism of POLE mutations on endometrial cancer." (PMID 31864301, 2019). "Mutations in POLE have been reported in colorectal and 10% of endometrial cancers." (PMID 31645345, 2019). "In addition, 15% of endometrial cancer patients had POLE somatic mutations as well, where more than 90% of POLE mutations were missense mutations." (PMID 31864301, 2019). "Somatic mutations in POLE have been found in endometrial cancers in many studies." (PMID 31864301, 2019).
endometrial cancer (continued). "The survival curve of endometrial cancer patients showed that the exclusion of patients with hypermutated phenotypes altered the effects of POLE mutations on patient prognosis, hence the POLE mutations were no longer significantly associated with improved prognosis." (PMID 31864301, 2019). "Collectively, our data demonstrated that endometrial cancer patients with POLE mutations might achieve improved clinical prognosis by regulating cellular glycometabolis." (PMID 31864301, 2019). "This study demonstrates that POLE-mutated endometrial cancer is significantly associated with previously unknown clinicopathologic characteristics." (PMID 30917185, 2019). "Endometrial cancer patients with POLE mutations had favorable prognoses, indicating that mutant POLE may play an important role in the development and progression of endometrial cancer." (PMID 31864301, 2019). "Although POLE exonuclease domain mutations have been reported to have a benign effect on prognosis in patients with endometrial cancer, little is known about the relationship and possible mechanism between the POLE mutational status and endometrial cancer patient prognosis." (PMID 31864301, 2019). "We demonstrated that POLE mutations improved prognosis in endometrial cancer patients." (PMID 31864301, 2019). "Furthermore, the patients with POLE-mutated dedifferentiated and undifferentiated endometrial carcinomas had a favorable outcome." (PMID 31370215, 2019). "The presence of APC mutations as an alternative to CTNNB1 mutations in some POLE‐mutant endometrial cancers is an exemplar, and there are likely to be others, such as NF1 and RB1 mutations in endometrial cancer and atypical (Q61P, K117 N, and A146T) KRAS mutations in colorectal cancer." (PMID 29604063, 2018). "The correlation of POLE mutation with PD1/PD-L1 immunotherapy in colorectal cancer and endometrial cancer leads us towards further research to explore whether there is a treatment option for immunotherapy in POLE-mutated IBC." (PMID 30086764, 2018). "A recent case report of a pathogenic POLE mutation in a endometrial cancer and its precursor 25 suggests that these mutations may occur early in tumour development, but the single case precludes generalization of this result." (PMID 29604063, 2018). "In endometrial cancers that are mutation burden rich because of POLE mutations, the immune checkpoint molecules are highly expressed, suggesting the possibility that immune checkpoint inhibitor treatment may be effective." (PMID 29464025, 2018). "Currently, we are investigating whether immune checkpoint inhibitors are also effective for Japanese endometrial cancer patients with POLE mutations." (PMID 29464025, 2018). "The Cancer Genome Atlas (TCGA) yielded four molecular subgroups of endometrial cancer (polymerase E catalytic subunit (POLE) ultra-mutated, MSI hyper-mutated, copy number (CN) low, and CN high), based on nucleotide substitution patterns and frequencies, MSI status, and copy number cluster." (PMID 30134578, 2018). "The incidence of POLE mutation in endometrial cancer patients is known to be 7–12%." (PMID 30134578, 2018). "Twelve missense somatic mutations predicted to affect the proofreading domain of POLE, and all associated with microsatellite stability, have also been identified in a study of 173 endometrial cancers, P286R being the most commonly represented (6 times) POLE mutation." (PMID 24705290, 2014). "Our results showed that overexpression of POLE variants remarkably promoted the metastatic abilities and altered the expression of EMT markers of endometrial cancer cells compared with wildtype POLE, suggesting that POLE mutations might contribute to endometrial cancer metastasis." (PMID 36313640, 2022).